ZNF658B (zinc finger protein 658B (pseudogene))
Description:
May be involved in transcriptional regulation.
Gene: Transcribed unprocessed pseudogene on chromosome 9 (39,444,304 to 39,508,885, reverse strand). Ensembl gene ENSG00000198416.
Subcellular location: Nucleus